DUSP2 (dual specificity phosphatase 2)
Description:
Dephosphorylates both phosphorylated Thr and Tyr residues in MAPK1, and dephosphorylation of phosphotyrosine is slightly faster than that of phosphothreonine. Can dephosphorylate MAPK1 (By similarity).
Synonyms: PAC1; PAC-1
Tractability: Small molecule: it has a high-quality binding pocket. PROTAC: ubiquitination databases record sites on it; a small molecule that binds it is known.
Target class: Phosphatase; Serine/threonine/tyrosine protein phosphatase; Enzyme; Protein Phosphatase
Gene: Protein-coding gene on chromosome 2 (96,143,166 to 96,145,440, reverse strand). Ensembl gene ENSG00000158050.
Subcellular location: Nucleus
Subcellular location (Human Protein Atlas): Nuclear membrane; Nucleoplasm
Pathways (Reactome):
Signal Transduction: Negative regulation of MAPK pathway; RAF-independent MAPK1/3 activation
Gene Ontology:
Molecular function: protein binding; protein serine/threonine phosphatase activity; protein tyrosine phosphatase activity; protein tyrosine/threonine phosphatase activity; MAP kinase tyrosine/serine/threonine phosphatase activity; mitogen-activated protein kinase binding; phosphoprotein phosphatase activity
Biological process: endoderm formation; protein dephosphorylation
Cellular component: nuclear membrane; nucleoplasm; nucleus
Genetic constraint (gnomAD): Loss-of-function variants: 20 observed, 20.14 expected, observed/expected ratio (o/e) 0.99, 90% interval 0.7 to 1.44. The synonymous counts are far from expectation, so gnomAD's model fits this gene poorly and the ratio says little. Missense variants: 435 observed, 361.01 expected, observed/expected ratio (o/e) 1.21, 90% interval 1.11 to 1.3. Synonymous variants: 231 observed, 168.81 expected, observed/expected ratio (o/e) 1.37, 90% interval 1.23 to 1.53.
Homologues: Orthologues: chimpanzee DUSP2 (99% identical), macaque DUSP2 (96% identical), dog DUSP2 (91% identical), guinea pig DUSP2 (91% identical), rabbit DUSP2 (91% identical), pig DUSP2 (89% identical), rat Dusp2 (89% identical), mouse Dusp2 (88% identical), zebrafish dusp2 (53% identical). Paralogues in human: DUSP1 (52% identical), DUSP4 (51% identical), DUSP5 (45% identical), DUSP9 (36% identical), DUSP7 (35% identical), DUSP6 (35% identical), DUSP16 (33% identical), DUSP8 (32% identical), DUSP10 (30% identical), SSH1 (25% identical), SSH2 (25% identical), SSH3 (23% identical), and 19 more.
Diseases named in the same sentence as DUSP2 in open-access papers:
DUSP2 is named in the same sentence as 80 diseases in open-access papers, as found by Europe PMC text mining. Sharing a sentence is not in itself a finding about the gene and the disease. The quoted sentences say what the papers report.
breast carcinoma (10 papers, 2012 to 2025). "For paclitaxel we found that three genes were reported to be associated with ovarian cancer (HOXB2, MYC, and TFPI2; p=0.024) and two genes were strongly associated with tumorigenesis of breast cancer (DUSP2 and ITGA3; p<0.001)." (PMID 29416679, 2018). "Since HIF-1α expression is associated with poor clinical outcome in breast cancer patients and we show that hypoxia via HIF-1α reduces DUSP2 expression, we interrogated whether DUSP2 expression may also be associate with poor clinical outcome in breast cancer patients." (PMID 25596742, 2015). "The results of RNA-seq showed that shikonin induces the expression of DUSP1 and DUSP2 in breast cancer cells." (PMID 29422643, 2018). "Hypoxia inducible factor-1 alpha (HIF1-alpha) has been shown to induce lapatinib-resistance in HER2-postive breast cancers by deregulating DUSP2 activity." (PMID 29100331, 2017). "Hypermethylation of DUSP2 and murine Dusp2 and has been reported in breast cancer cell lines, however methylation in primary human mammary tumors was absent, which was also observed in our study." (PMID 26833217, 2016). "In 12 breast carcinoma, 20 pheochromocytoma and six small cell lung cancer samples the DUSP2 promoter was unmethylated." (PMID 26833217, 2016). "Consistent with its regulation of ERK, DUSP2 downregulation correlated with increased ERK activation in breast cancer cells placed under hypoxic conditions." (PMID 25596742, 2015). "Here, we demonstrate for the first time that hypoxia promotes lapatinib resistance in ERBB2-positive breast cancer cells through activation of the MEK-ERK pathway in a HIF-1-dependent manner via regulation of DUSP2." (PMID 25596742, 2015). "We examined DUSP2 expression in three different ERBB2 expressing breast cancer cell lines and observed that DUSP2 protein levels are downregulated under hypoxic conditions." (PMID 25596742, 2015). "Also, the results of qRT-PCR confirmed that shikonin induced the expression of both DUSP1 and DUSP2 in different types of breast cancer cells." (PMID 29422643, 2018). "Therefore, we suggest that shikonin induces the expression of DUSP1 and DUSP2 which consequently switches off JNK and p38 MAPK pathways and causes cell cycle arrest and apoptosis in breast cancer cells." (PMID 29422643, 2018). "Therefore, our results suggest that shikonin induces the expression of DUSP1 and DUSP2 which consequently switches off JNK and p38 MAPK pathways and causes cell cycle arrest and apoptosis in breast cancer cells." (PMID 29422643, 2018). "Moreover, our experimental results also demonstrated that shikonin induced the protein expression of both DUSP1 and DUSP2 in different types of breast cancer cells." (PMID 29422643, 2018). "Moreover, hypoxia/HIF1α induces lapatinib resistance in HER2-positive breast cancer cells via regulation of DUSP2 and HIF-1 can bypass the lapatinib-treated inhibition of the ERK pathway via inhibition of the dual-specificity phosphatase 2 (DUSP2)." (PMID 29410730, 2017). "We detected increased DUSP2 methylation (level ≥5 %) in lung cancer (A427, H322, A549), breast cancer (MCF-7, ZR75-1), melanoma (SKMel13, IGR1, buf1280, SKMel28, MeWo), ovarian cancer (Skov, Ovar, ES2, OAW42), hepatocarcinoma (Hep2G) and sarcoma (LMS6/93, U2OS) cell lines." (PMID 26833217, 2016). "Indeed, overexpression of DUSP2 in ErbB2-positve breast cancer cells reverses hypoxia-mediated lapatinib resistance." (PMID 25596742, 2015). "Moreover, MCF10A-ERBB2 cells expressing HIF-1α RNAi abrogated DUSP2 downregulation under hypoxia, thus regulation of DUSP2 by hypoxia in breast cancer cells is HIF-1α-dependent." (PMID 25596742, 2015). "To test whether increasing DUSP2 levels could sensitize hypoxic breast cancer cells to lapatinib, we stably overexpressed Flag-tagged DUSP2 in MCF10A-ErbB2 cells." (PMID 25596742, 2015).
breast carcinoma (continued). "Indeed, the expression of a stable HIF-1α mutant or reduction of DUSP2 via RNAi can promote lapatinib resistance in breast cancer cells under normal oxygen tension." (PMID 25596742, 2015). "We analyzed the promoter hypermethylation of DUSP2 in primary tumors including Merkel cell carcinoma (MCC), pheochromocytoma, small cell lung cancer and breast carcinoma by COBRA." (PMID 26833217, 2016). "We examined expression of DUSP2 in ERBB2-positive breast cancer samples using Kaplan-Meier Plotter and found that in 207 ERBB2-positive breast cancer patients with reduced DUSP2 levels showed a decreased trend in relapse-free survival that was not significant (p = 0.15)." (PMID 25596742, 2015).
colon cancer (7 papers, 2011 to 2022). "Additionally, DUSP2 suppression was associated with tumorigenesis and malignancy in colon cancer, and DUSP2 overexpression induced apoptosis and inhibited tumor growth in HeLa cells in vitro and in xenograft models." (PMID 22118688, 2011). "DUSP2 is expressed at low levels in a variety of tumors, such as prostate cancer, pancreatic cancer, colon cancer, and leukemia, and it participates in the regulation of tumor development through various signaling pathways." (PMID 35295342, 2022). "In colon cancer, chronic hypoxia intensifies the expression of dual specificity phosphatase 2 (DUSP2), a nuclear phosphatase which reduces the activation of MAPK cascades." (PMID 33467722, 2021). "As the potential ability to dephosphorylate proteins, several DUSPs have been shown to play critical roles in human cancers, such as DUSP2 in colon cancer, DUSP6 in lung cancer, and DUSP8 in hepatocellular carcinoma." (PMID 33718185, 2021). "In colon cancer, dual specificity phosphatase-2 (DUSP-2) was suppressed by hypoxic culture, which led to the upregulation of COX-2 expression." (PMID 31709180, 2019). "Fifteen genes (DUSP2, INFGR1, IL6, IRF2, JAK2, MAP3K10, MMP1, NFkB1A, NOS2A, PIK3CA, SEPX1, SMAD3, TLR2, TYK2, and VDR) were significantly associated with colon cancer mortality at the <0.05 level; an additional 15 genes had gene PARTP values between 0.05 and 0.10." (PMID 25541970, 2014). "Fifteen genes (DUSP2, INFGR1, IL6, IRF2, JAK2, MAP3K10, MMP1, NFkB1A, NOS2A, PIK3CA, SEPX1, SMAD3, TLR2, TYK2, and VDR) were associated with colon cancer mortality (PARTP <0.05); JAK2 (PARTP = 0.0086), PIK3CA (PARTP = 0.0098), and SMAD3 (PARTP = 0.0059) had the strongest associations." (PMID 25541970, 2014). "By contrast, decreased DUSP2 transcript levels were reported in cancerous breast, colon, lung, ovary, kidney and prostate tissues, and reduced DUSP2 protein levels were observed in cervical and colon cancer." (PMID 22118688, 2011).
gastric cancer (7 papers, 2021 to 2025). A primary or metastatic malignant neoplasm involving the stomach. "The effects of SKA3 and DUSP2 on the proliferation, migration, invasion, adhesion, and epithelial-mesenchymal transition of gastric cancer were studied in vitro and in vivo." (PMID 35295342, 2022). "Similarly, gastric cancer-derived exosomal miR-519a-3p targets DUSP2, activating the MAPK/ERK pathway and inducing macrophage M2-like polarization, which accelerates gastric cancer liver metastasis." (PMID 39979806, 2025). "In addition, another study found that gastric cancer-derived EV miR-519a-3p activates the MAPK/ERK pathway by targeting DUSP2, which leads to M2-like polarization of macrophages, ultimately leading to gastric cancer liver metastasis." (PMID 38037077, 2023). "In the study of Zhang, decreased miR-616-5p could promote cell viability and inhibit apoptosis via downregulating the DUSP2 expression in gastric cancer." (PMID 34956884, 2021). "Mechanistically, SKA3 negative regulates the tumor suppressor DUSP2 and activates the MAPK/ERK pathway to promote gastric cancer." (PMID 35295342, 2022). "Exosome-associated transfer of miR-519a-3p from gastric cancer cells to intrahepatic macrophages induces M2 polarization of macrophages by suppressing Dual specificity protein phosphatase 2 (DUSP2) and escalating MAPK/ERK pathway, thus enhancing PMN formation and liver metastasis in gastric cancer." (PMID 38741166, 2024).
pancreatic cancer (5 papers, 2018 to 2024). "Consistently, the DUSP2 protein level was significantly reduced in miR-361-3p mimic-transfected pancreatic cancer cells but was increased in miR-361-3p-knockdown cells." (PMID 30042387, 2018).
bladder cancer (4 papers, 2019 to 2025). "MiR-340-5p, a microRNA with context-dependent tumour suppressor or oncogenic functions, was significantly negatively correlated to DUSP2 expression in various cancer types like in thymoma, brain tumours, colorectal and bladder cancer as well as in lymphoma." (PMID 40537745, 2025). "DUSP2 encodes a phosphatase that deactivates protumorigenic MAP-kinases, the loss of which predicts a poor prognosis in bladder cancer." (PMID 35892849, 2022). "DUSP2 levels are significantly decreased in bladder cancer and low expression of DUSP2 is correlated with poor prognosis." (PMID 31827401, 2019).
Arthritis (3 papers, 2014 to 2021). Inflammation of a joint. "DUSP2 positively regulated autoimmune responses in an arthritis animal model." (PMID 26273834, 2015).
autoimmune disease (3 papers, 2019 to 2026). A disorder resulting from loss of function or tissue destruction of an organ or multiple organs, arising from humoral or cellular immune responses of the individual to their own tissue constituents. "In addition, DUSPs are also involved in either human autoimmune diseases (DUSP2, DUSP7, DUSP10, and DUSP12) or T-cell activation (DUSP1, DUSP5, and DUSP14)." (PMID 31766293, 2019). "Besides DUSP22 downregulation in SLE patients, other DUSPs (DUSP2, DUSP7, DUSP10, and DUSP12) are also downregulated or mutated in human autoimmune diseases." (PMID 31766293, 2019). "DUSP2, DUSP4, DUSP7, DUSP10, DUSP12, DUSP22, and DUSP23 are involved in human autoimmune diseases, including SLE." (PMID 31766293, 2019). "Besides autoimmune diseases, reduction of DUSP1, DUSP2, and DUSP14, as well as induction of DUSP8 contribute to the pathogenesis of allergic diseases." (PMID 42087139, 2026).
inflammatory bowel disease (3 papers, 2023 to 2026). A spectrum of small and large bowel inflammatory diseases of unknown etiology. "Additionally, decreased levels of DUSP2, DUSP11, DUSP22, and DUSP28 are associated with human inflammatory bowel diseases." (PMID 42087139, 2026). "PAC1 is overexpressed in inflammatory bowel disease and rheumatoid arthritis, and mice lacking the expression of PAC1/Dusp2 exhibit impaired inflammatory responses and protection from arthritis." (PMID 36662585, 2023).
lymphoma (3 papers, 2020 to 2025). A malignant (clonal) proliferation of B- lymphocytes or T- lymphocytes which involves the lymph nodes, bone marrow and/or extranodal sites. "Additionally, recent findings show that these miRNAs can downregulate dual specificity phosphatase 2 (DUSP2), further contributing to oncogenic signaling in lymphoma models." (PMID 40981381, 2025). "Predicted interactions of microRNAs with the DUSP2 3’UTR were verified using reporter gene assays and functionally validated in a lymphoma cell model." (PMID 40537745, 2025). "Furthermore, treatment of the lymphoma cell line WSU-DLCL2 with microRNA inhibitors for miR-17-5p, miR-20b-5p, or miR-106b-5p resulted in increased DUSP2 mRNA levels." (PMID 40537745, 2025).
nasopharyngeal carcinoma (3 papers, 2024 to 2025). A carcinoma arising from the nasopharyngeal epithelium. "Targeting DNTTIP1/HDAC1 using chidamide disrupts the ERK signaling pathways and decreases MMP2 expression by upregulating dual specificity phosphatase 2 (DUSP2); this inhibits the migration, invasion, and proliferation of nasopharyngeal carcinoma cells." (PMID 38315203, 2024). "HDAC1 can be recruited to the promoter of DUSP2 gene to maintain a deacetylated state of histone H3K27, which leads to the silencing of DUSP2 and elevated MMP2 level to promote nasopharyngeal carcinoma metastasis." (PMID 38374872, 2024).
ovarian carcinoma (3 papers, 2012 to 2018). A malignant neoplasm originating from the surface ovarian epithelium. "The overexpression of DUSP2 in ovarian cancers has been correlated with poor outcome." (PMID 22646717, 2012).
pancreatic ductal adenocarcinoma (3 papers, 2018 to 2022). An infiltrating adenocarcinoma that arises from the epithelial cells of the pancreas. "DUSP2 also has been demonstrated to be involved in EMT through its direct involvement in the inactivation of the extracellular signal-regulated kinase pathway in pancreatic ductal adenocarcinoma, which is essential to the epithelium-originated solid tumor metastasis cascade." (PMID 31467637, 2019).
prostate carcinoma (3 papers, 2022 to 2025). A carcinoma that arises from epithelial cells of the prostate gland. "DUSP2 is an important regulator of immune responses, and its low expression has been detected in various tumors, such as prostate cancer, glioma, and leukemia." (PMID 35295342, 2022).
asthma (2 papers, 2021 to 2023). "Our analysis indicated that DUSP2 was potentially associated with steroid-resistant asthma." (PMID 37208441, 2023). "Since our study suggested that DUSP2 was upregulated in the BAL cells of SR asthma patients as compared with SS asthma patients, we further investigate the role of DUSP2 on steroid-resistant asthma." (PMID 37208441, 2023). "It is necessary to further delineate the pathogenesis role of DUSP2 in steroid-resistant asthma." (PMID 37208441, 2023). "Our study not only provides an insight into the role of DUSP2 and its inhibitor (salubrinal) in steroid-resistant neutrophilic airway inflammation but also lay a foundation for the development of alternative therapy options in steroid-resistant asthma." (PMID 37208441, 2023). "However, few studies have reported the role of DUSP2 in steroid-resistant asthma." (PMID 37208441, 2023). "Therefore, we hypothesized that inhibition of DUSP2 showed a protective effect on the airway inflammation of steroid-resistant asthma." (PMID 37208441, 2023). "DUSP2 may be a candidate target for the therapy of steroid-resistant asthma." (PMID 37208441, 2023). "However, few studies have investigated the role of DUSP2 in steroid-resistant asthma." (PMID 37208441, 2023). "The top six upregulated DEG genes (IL6, CXCL8, TNF, DUSP2, ADM, and CXCL1) in SR asthma patients compared with SS asthma patients were identified." (PMID 37208441, 2023). "In our study, we observed that the salubrinal administration (DUSP2 inhibitor) reversed neutrophilic airway inflammation and cytokine responses (IL-17A, TNF-α) in a steroid-resistant asthma mouse model." (PMID 37208441, 2023). "DUSP2, as one of the top upregulated DEGs, has not been clearly demonstrated in steroid-resistant asthma." (PMID 37208441, 2023). "Besides, we first demonstrated that salubrinal reduced LPS-driven CXCL10 expression in J774A.1 macrophage, indicating the interaction between DUSP2 and CXCL10 may be the potential mechanism for steroid-resistant asthma." (PMID 37208441, 2023).
B-cell lymphoma (2 papers, 2019 to 2023). "The observation that DUSP2 expression is highly inducible upon stimulation of B-cell lymphoma cell lines suggests that mutations in DUSP2 may have the potential to modify MAPK signalling in DLBCL." (PMID 30401534, 2019). "Mutational profiling using a custom panel of 168 genes associated with aggressive B-cell lymphomas confirmed mutations in ACTB, ARID1B, DUSP2, DTX1, HLA-B, PTEN, and TNFRSF14." (PMID 36975733, 2023).
diffuse large B-cell lymphoma (2 papers, 2019 to 2025). "In the next step, the influence of selected microRNAs (miR-17-5p, miR-20b-5p, miR-106b-5p) on DUSP2 mRNA level was validated in WSU-DLCL2 cells a cell line derived from a diffuse large B-cell lymphoma (DLBCL)." (PMID 40537745, 2025).
endometriosis (2 papers, 2018 to 2024). The growth of functional endometrial tissue in anatomic sites outside the uterine body. "In endometriosis, hypoxia stabilizes hypoxia inducible factor-1α (HIF1A) which downregulates dual-specificity phosphatase-2 (DUSP2) directly and indirectly through miR-20a." (PMID 30087267, 2018).
hepatocellular carcinoma (2 papers, 2021 to 2025). A malignant tumor that arises from hepatocytes. "Likewise, the newly identified interaction between mir-122-5p and DUSP2 should be the subject of future studies since a significant negative correlation was found in hepatocellular carcinoma while miR-122-5p is primarily regarded as a liver-specific tumour suppressor i.a. by downregulation of DUSP4." (PMID 40537745, 2025).
lung carcinoma (2 papers, 2016 to 2021). "An increase in methylation of DUSP2 was also found in 17 out of 24 (71 %) cancer cell lines, including skin and lung cancer." (PMID 26833217, 2016). "Overexpresssion of the CTCF construct with mutated SUMOylation sites in the CTCF N-terminus or C-terminus resulted in a lack of DUSP2 reactivation in the lung cancer H322 and HEK293 cells." (PMID 26833217, 2016).